CYP1B1 (cytochrome P450 family 1 subfamily B member 1)
Diseases named in the same sentence as CYP1B1 in open-access papers (continued):
Sharing a sentence is not in itself a finding about the gene and the disease.
tumor (continued). "CYP1B1 showed statistically significant downregulation across the tumor stages at the transcriptional level in 28/36 pairs as analyzed by qRT-PCR." (PMID 22114726, 2011). "In summary, the CYP1B1 downregulation in oral tumor tissues as compared to their matched normal tissues contradicts many studies which state that CYP1B1 is overexpressed in tumors." (PMID 22114726, 2011). "It is evident from the Immunohistochemistry as well as the Western blot analysis that the CYP1B1 proteinis expressed in all normal tissues analysed and ispredominantly downregulated in tumor tissues." (PMID 22114726, 2011). "The activation of the prodrug facilitated by CYP1B1 would enable the targeting of chemotherapy to tumor tissues in which CYP1B1 is specifically overexpressed as a result reducing the non-specific side effects that the current chemotherapy elicits." (PMID 22114726, 2011). "Second, rapid mammary growth would facilitate expansion of Cyp1b1-expressing mammary epithelial cell populations into tumor cells." (PMID 20435547, 2010). "The most significant finding of this research group was the identification of the enzyme CYP1B1 as a tumor marker, since the CYP1B1 protein was detected in a vast range of tumor tissues, irrespective of their oncogenic origin." (PMID 19531241, 2009). "The cytochrome P450 CYP1B1 is consistently overexpressed in tumour cells as compared to their normal counterparts, but its precise role in drug resistance is yet to be defined." (PMID 18212750, 2008). "The tumour marker CYP1B1 was also decreased by 71.5% in tumour tissue from combination-treated mice as compared with vehicle control as shown by western blotting and immunohistochemistry." (PMID 18797454, 2008). "The role of CYP1B1 in tumour suppression was also shown in a study where CYP1B1 null mice were protected against DMBA-induced tumours as compared with their wild-type counterparts." (PMID 18797454, 2008). "The presence of detectable CYP1B1, which is capable of metabolising anticancer drugs in tumour cells, highlights a novel target for therapeutic intervention." (PMID 15280921, 2004). "Both CYP1B1 and P450R can catalyse the biotransformation of anticancer drugs at the site of the tumour." (PMID 15280921, 2004). "The enzyme CYP1B1 is overexpressed in a wide variety of human tumours and catalyses aromatic hydroxylation reactions." (PMID 11875742, 2002). "CYP1B1 is a tumour-related form of cytochrome P450 which is over expressed in a wide variety of primary tumours of different histological type." (PMID 11461084, 2001). "Tumor stage after NAC was significantly associated with both ITC density and CYP1B1 histoscore." (PMID 40478625, 2025). "However, knockdown of CYP1B1 reduced the tumour volume and significantly enhanced the inhibitory effect of sunitinib on tumour growth." (PMID 40435846, 2025). "Given that CYP1B1 is a key molecule in angiogenic signalling pathways, we hypothesized that it may play a significant role in regulating VM and tumour angiogenesis." (PMID 40435846, 2025). "This selectivity is crucial: by targeting an enzyme predominantly expressed in tumor tissue, PA might exert anticancer effects while sparing most normal physiological processes (CYP1B1 is minimally expressed in most normal organs)." (PMID 40883330, 2025). "Although individual reports have recently shown that CYP1B1 is likely to affect tumor progression by regulating ferroptosis level, the potential role of CYP1B1 in ferroptosis modulation in ECC cells remains unclear." (PMID 39478199, 2025). "Furthermore, CYP1B1 significantly influences CRC liver metastasis by regulating tumor cell proliferation through the “CYP1B1-LCFAs-G1/S transition,” suggesting its potential as a therapeutic target for CRC liver metastasis." (PMID 41158511, 2025). "Consequently, tumour-associated CYP450 isoforms, such as CYP1A1, CYP1B1, CYP2S1, and CYP2W1—have become a focus for the development of novel anticancer therapies." (PMID 41174467, 2025).
tumor (continued). "In conclusion, high ADAM12 and CYP1B1 expressions in the peritumoral adipocytes boost tumor invasiveness and may serve as an indicator of poor prognosis in RCC." (PMID 39806854, 2025). "Therefore, CYP1B1 seems to be more predictive of tumor development than an independent predictor of prognosis." (PMID 41155673, 2025). "Interestingly, the association between CYP1B1 and post-NAC tumor stage was driven entirely by the TCE-TNBC subset." (PMID 40478625, 2025). "Furthermore, CH223191 also significantly reduced the expression of CYP1B1, another target gene of AhR, suggesting that AhR inhibition was more effective, which was consistent with the results of tumour growth suppression." (PMID 40759641, 2025). "However, there have been conflicting reports regarding the expression of CYP1B1 in tumors vs. the adjacent non-tumor mammary gland tissues." (PMID 40807256, 2025). "The results revealed increased ABCB1 and CYP1B1 expression in tumor samples of the poor responders." (PMID 38534761, 2024). "Similarly, it has been shown that cytochrome p450 1b1 (Cyp1b1) is overexpressed in many neoplasms and plays an important role in developing resistance to chemotherapy." (PMID 38026933, 2023). "However, when we performed an analysis of CYP1B1 expression in tumor tissue and its normal counterpart deriving from the same subject, we found that CYP1B1 is more expressed in normal tissue than in tumoral tissue." (PMID 37371125, 2023). "In addition, AhR inhibition by SR1 downregulated Cyp1a1, Cyp1b1 and Runx1 expression in MEPs in tumor-bearing mice." (PMID 37919525, 2023). "Single cell RNA sequencing identifies a subset of tumor-associated aHSC expressing Cyp1b1 but no other 12-HHTrE biosynthetic genes." (PMID 37156770, 2023). "CYP1B1 is highly expressed in CRC tumor tissues and is related to poor prognosis." (PMID 37059712, 2023). "However, there were no significant changes in the expression levels of AHR signaling pathway-related molecules, including AhR, AhRR, Cyp1a1, Cyp1a2, Cyp1b1 and Cox2, in tumor-infiltrating neutrophils from Arnt−/− mice." (PMID 36859266, 2023). "Anti-mPD-1 treatment significantly inhibited tumor growth in mice bearing CYP1B1 knockdown tumors." (PMID 37059712, 2023). "Given that elevated levels of CYP1B1 were observed in multiple cancers, astilbin could also exert anti-tumor activity via targeting CYP1B1 to induce apoptosis by producing high levels of ROS." (PMID 35652039, 2022). "The 3’-untranslated region of CYP1B1 is also a target of various miRNAs whose regulation could impact CYP1B1 expression in various tumor cells." (PMID 36230892, 2022). "Based on these findings, we speculated that CYP1B1 may regulate the immune cell infiltration in the tumor microenvironment, which could act as a molecular marker for clinical therapy." (PMID 36428734, 2022). "In vitro and vivo function experiments identified that CYP1B1 could increase tumor progression and metastasis." (PMID 36428734, 2022). "Two studies contradict this model and indicate that CYP1B1 expression may play a significant role in tumor progression." (PMID 36077068, 2022). "Thus, while the establishment of the IDO/TDO tumor progression circuit seems unlikely, the overexpression of CYP1B1 nonetheless drove EMT in these cells." (PMID 36077068, 2022). "Analysis of the 311 tumor samples showed significant differences in overall and disease-free survival when the samples were grouped by tertiles into either high versus low expression of CYP1B1." (PMID 36077068, 2022). "The dysregulated expression of CYP1B1 was explored between tumor and normal tissues." (PMID 36428734, 2022). "The first tumor-accelerated responses at 1 h after TPA treatment began with genes in “deregulated cellular metabolism”, with the up-regulation of CYP1a1 and CYP1b1, and with genes in “tumor-promoting inflammation”, with the up-regulation of prostaglandin E synthase in prostanoid biosynthesis." (PMID 35328637, 2022).
tumor (continued). "Importantly, strong CYP1B1 differential expression between normal and tumor cervical tissues makes it a potential therapeutic target for the development of novel CYP1B1-based therapeutic strategies." (PMID 34636736, 2021). "On a genetic level, a comparable study in a set of 20 paired samples of tumour and adjacent normal breast tissues from patients with infiltrating ductal carcinoma identified the expression of CYP1B1, CYP2B6, CYP2C, CYP2D6, CYP2E1, CYP4B1 and CYP11A1 in both tumour and control tissues." (PMID 33809117, 2021). "However, there have been conflicting reports regarding the expression of CYP1B1 in tumours vs. the adjacent non tumour mammary gland tissues." (PMID 33809117, 2021). "Thus, the differential and tumor-specific expression of CYP1B1 provides a novel potential for the development of new anticancer therapeutics." (PMID 34636736, 2021). "Further studies are required to look deeply into the mechanistic role of CYP4Z1 and CYP1B1 in tumour progression and to better validate whether they are druggable targets." (PMID 33692504, 2021). "Several reports indicate expression of CYP4Z1 and CYP1B1 in many tumours." (PMID 33692504, 2021). "Therefore, the differential and tumour selective expression of CYP1B1 represents a novel opportunity for the development of new anticancer therapeutic strategies." (PMID 33692504, 2021). "Additionally, in vitro and in vivo studies using tumor cell line models have shown that CYP1B1 overexpression promotes cell invasion, migration, and proliferation, and hampers cell death." (PMID 34636736, 2021). "Importantly, CYP1B1 has recently been proposed as a universal tumor antigen owing to its selective overexpression in tumors compared to negative or undetectable levels of protein expression in the corresponding normal tissues." (PMID 34636736, 2021). "5-HETE and 15-HETE, in particular have been shown to induce cell growth and proliferation in vitro in various tumor-derived cell lines, implying a function for these compounds, and thus CYP1B1, in prostate tumor growth and proliferation." (PMID 32581794, 2020). "In CAL27 cells, the growth of CYP1B1-WT tumours was much more rapid than that of p15 tumours, and the difference was significant 14 days post transplantation; the growth of CYP1B1-VAR tumours was even faster, but the difference between CYP1B1-WT and CYP1B1-VAR tumours remained below significance." (PMID 32565541, 2020). "CYP1B1 expression was associated with tumor stage and progression, but not with the histological grade (p = 0.375)." (PMID 32907554, 2020). "The effect of CYP1B1 on tumor formation and growth may be further exacerbated by the simultaneous production of EETs and mid-chain HETEs." (PMID 32581794, 2020). "Similarly, CYP1B1 was shown to be expressed in eight different cell lines that represent four tumor tissues, with the highest expression levels manifested in HeLa, SKOV-3, and MDA-MB-231 cells, respectively." (PMID 33185690, 2020). "Cytochrome P450 1B1 (CYP1B1) is mostly expressed in tumours and displays unusual properties." (PMID 32565541, 2020). "In addition, miR‐187‐5p is a tumour suppressor miRNA in non‐small lung cancer progression, overexpression of miR‐187‐5p can significantly inhibit the expression of CYP1B1 and reduce the growth and metastasis of non‐small lung cancer." (PMID 32845093, 2020). "Furthermore, Jung Kwon and colleagues measured different markers of tumor progression, including cell proliferation, invasion, and cell migration after CYP1B1 modulation, induction, or inhibition." (PMID 32626511, 2020). "AF induced CYP1A1 and CYP1B1 gene expression in human tumor renal cell lines." (PMID 32443455, 2020). "On the basis of previous data showing that 3MC induces CYP1B1 expression in tumor cells through AHR, we aimed to evaluate whether GPER may be involved in the expression of CYP1B1 by 3MC." (PMID 31370872, 2019).
tumor (continued). "CYP1B1, the biggest known human P450 protein in terms of size of mRNA and amino acids, is highly expressed in tumour cells and studies have highlighted its important role in tumour development." (PMID 31382511, 2019). "Worthy, the CYP1B1 inhibitor TMS prevented the stimulatory effects on tumor growth exerted by estrogenic GPER signaling both in vitro and in vivo, in accordance with previous studies that highlighted the ability of this agent to delay tumor progression in xenograft models." (PMID 29290975, 2017). "Tumor-specific overexpression of CYP1B1 indicates its role as a regulator of tumor progression." (PMID 28388569, 2017). "However, we still know little about the exact mechanism of CYP1B1 gene SNPs interacting with tumor development." (PMID 28377924, 2017). "Therefore, CYP1B1 has been recognized as a potential tumor biomarker and a promising target for anticancer therapy." (PMID 28388569, 2017). "It has been suggested that CYP1B1 may be important in tumor development and progression, and also contributes to drug resistance." (PMID 25860934, 2015). "We further assessed whether CYP1B1 expression in clinical samples are correlated with clinicopathologic characteristics such as tumor types, stage and Fuhrman grade." (PMID 25860934, 2015). "In addition, a significant difference was also observed between RCC tumors with moderate and low CYP1B1 levels (3.36±0.50 versus 5.14±0.58 in tumor samples with weak CYP1B1 expression)." (PMID 25860934, 2015). "The xenobiotic metabolising forms of P450 have been extensively studied in tumours and many individual members have been shown to be overexpressed in specific types of tumours most notably CYP1B1 which has been shown to have increased expression in a wide range of tumours." (PMID 24608339, 2014). "Among the upregulated genes, we identified several oncogenes (Ets2, Fyn, Fos, Rab30 and Src), various tumor markers (Cyp1b1, Gpa33, Cd47, Fam129a, st7l, chka, Lgalsbp, Antxr1 and Ly6a) and other genes related to tumor promotion (Cxcl10, Trim25, Grn, Foxc2, Bmp7 and Irs1)." (PMID 23936067, 2013). "Based on the primary analysis of CYP1-mediated metabolism of diosmetin in human tumors we hypothesized that active CYP1B1 is expressed at higher levels in tumor samples." (PMID 24358191, 2013). "Apart fromAhRR, epigenetic modifications such as promoter methylation of CYP1B1 in tumor tissues could also account for the downregulation of CYP1B1." (PMID 22114726, 2011). "The reason behind the observed downregulation of CYP1B1 in tumor tissues can only be speculated upon." (PMID 22114726, 2011). "However, contrasting observations have been made with respect to the expression of CYP1B1 in OSCC tumor tissues." (PMID 22114726, 2011). "All the 36 matched tumor and normal tissue pairs analysed showed the expression of CYP1B1 mRNA." (PMID 22114726, 2011). "It is possible that the increased levels of CYP1B1 reported in tumour as compared to normal tissue are simply due to the fact that the expression of this enzyme is associated with carcinogenesis and/or with the resistant phenotype, rather than being directly involved in drug resistance." (PMID 18212750, 2008). "Therefore, to have a fuller understanding of the importance of CYP1B1 as a therapeutic target in tumours, it is important to determine the level of active CYP1B1 and P450R." (PMID 15280921, 2004). "CYP1B1 has been identified in a wide range of histologically distinct human neoplasms." (PMID 15280921, 2004). "The presence of metabolically active CYP1B1, which is overexpressed in tumours and which is capable of metabolising anticancer drugs within the tumour cells offers tremendous opportunities for the development of novel prodrugs activated by CYP1B1 only in the tumour cells." (PMID 15280921, 2004). "Indeed, several classes of prodrug, designed to be activated selectively by CYP1B1 at the site of the tumour, are currently in preclinical evaluation." (PMID 15280921, 2004).
tumor (continued). "The lower expression of the CYP1B1 gene in cancerous tissue relative to adjacent tissue could also be attributed to the possible downregulation of the gene by the AhR repressor in the tumor or by methylation of the promoter region, resulting in epigenetic silencing." (PMID 40807256, 2025). "Additionally, some studies have proposed that Mel may be metabolised by CYP1B1 within tumour mitochondria, producing N‐acetylserotonin (NAS)." (PMID 40804775, 2025). "Importantly, high CYP1B1 expression was found in younger patients (≤34 years; p = 0.013), but no other associations with tumor grade, size, or metastasis were observed." (PMID 41155673, 2025). "Importantly, the clinical relevance of this axis is underscored by our findings that CYP1B1 knockdown restored sunitinib sensitivity in vivo and that combined CYP1B1 inhibition and sunitinib treatment yielded tumour suppression effects superior to those of monotherapy." (PMID 40435846, 2025). "As was delineated in the introductory section, estrogen metabolism catalyzed by CYP1A1 and CYP1B1 leads to the formation of reactive intermediates, such as E2–4-hydroxy derivatives and quinones, which bind to DNA, forming DNA adducts: the important event in tumor initiation." (PMID 40807256, 2025). "Moreover, estrogen metabolism catalyzed by CYP1A1 and CYP1B1 leads to the formation of reactive intermediates, such as E2-4-hydroxy derivatives and quinones, which bind to DNA, forming DNA adducts, the important event in tumor initiation." (PMID 39339278, 2024). "Furthermore, inhibiting CYP1B1 sensitized tumor cells to anti-PD-1 antibody in a mouce model." (PMID 37059712, 2023). "Additionally, the role of CYP1B1 is also described in tumor proliferation and metastasis." (PMID 37059712, 2023). "Thus, during the hypoxia simulated by means of CoCl2 in patient-derived tumor primary cultured cells, the expression of genes HIF-1α and AhR changed unidirectionally, whereas AhR and CYP1B1 expressions were activated by the inducer (B[a]P) only during the hypoxic state of the cultured tumor cells." (PMID 37305351, 2023). "The increasing expression of CYP1A1 and CYP1B1 is related to the AHR pathway and causes the production of electrophilic derivatives by cytochrome P450 metabolizing enzymes to form DNA adducts, resulting in the activation of oncogenes and inactivation of tumor suppressor genes." (PMID 34784845, 2021). "This might reduce the CYP1B1 activity and result in tumour initiation or disease recurrence." (PMID 33906328, 2021). "The association of the aryl hydrocarbon receptor (AhR) with immune suppression in the tumour microenvironment may be mediated by the AhR-induced cytochrome P450 (CYP)1b1-driven ‘backward’ conversion of melatonin to its immediate precursor N-acetylserotonin (NAS)." (PMID 33375613, 2020). "Indeed, the use of tumor-bearing animal models is strongly needed to discern these divergent signaling pathways underpinning the cardioprotective and the chemo/radio-sensitizing effects of CYP1B1 inhibitors in the same animal model." (PMID 33185690, 2020). "Indeed, AHR-driven CYP1B1 was proposed as a universal tumor marker that could be immunologically targeted with CYP1B1-derived peptide vaccines." (PMID 33396563, 2020). "We selected these genes because all six were present in the angiogenesis signature unique to PDAC, because CYP1B1 was the most significantly and highly up-regulated, and because ANGPT1, its receptors TIE1 and TEK, and HIF1A are commonly associated with pathways that enhance tumor angiogenesis." (PMID 26586478, 2016). "Moreover, incubation of tumor microsomal protein in 4 bladder and 3 colon samples with a CYP1B1 specific antibody revealed a large reduction (72.5 ± 5.5 % for bladder and 71.8 ± 7.2% for colon) in catalytic activity, indicating that the activity was mainly attributed to CYP1B1 expression." (PMID 24358191, 2013).